ASPM (assembly factor for spindle microtubules)
Diseases named in the same sentence as ASPM in open-access papers (continued):
Sharing a sentence is not in itself a finding about the gene and the disease.
tumor (continued). "In addition, we evaluated the progression-free interval (PFI) and confirmed that ASPM was a high-risk gene in 25 tumor types." (PMID 40979592, 2025). "To summarize, we found that ASPM, CCNB2, and CDK1 expressions were significantly associated with tumor purity, which could be a sign that ASPM, CCNB2, and CDK1 played specific roles in immune infiltration in ACC." (PMID 35693556, 2022). "Although previous study mentioned the potential role of ASPM in tumor metastasis, the underlying mechanism is unknown." (PMID 34428354, 2021). "We also found that up‐regulation of ASPM in HCC was associated with vascular invasion and tumor embolus, indicating that ASPM may be involved in HCC invasion and metastasis." (PMID 34428354, 2021). "Interestingly, we reported that ASPM promoted the proliferation of LSCC in vitro and in vivo, and further found that ASPM expression was associated with tumor size and clinical stage, indicating a tight link between ASPM and LSCC." (PMID 32742488, 2020). "Interestingly, our findings of different cytoplasmic ASPM expression levels and associations with tumour stage among two subtypes reflect recent findings in the literature." (PMID 24830737, 2014). "High levels of ASPM in the cytoplasm were associated with reduced tumour grade, whereas high nuclear levels of microcephalin and an absence of cytoplasmic microcephalin was associated with better survival and lower tumour grade." (PMID 21505456, 2011). "We hypothesised that as mitosis- and DNA repair-associated proteins, ASPM and microcephalin, might have a role in the tumourigenesis of cancers with highly aneuploid tumours, such as high-grade EOC." (PMID 21505456, 2011). "Since the high expression of ASPM was associated with worse prognostic features and outcomes and, given that it is linked to tumor cell proliferation, we hypothesized that ASPM overexpression could play a significant role in resistance to radiotherapy and chemotherapy." (PMID 39594769, 2024). "In addition, ASPM is also implicated in tumorigenesis and tumour progression." (PMID 32667745, 2020). "In addition, ASPM mRNA upregulation was identified in 66% (162/247) of hepatocellular carcinomas, an observation associated with increased invasion, high stage and early tumour recurrence." (PMID 24830737, 2014). "For disease-specific survival (DSS), the results showed that ASPM also played a key role in DSS in 15 tumor types." (PMID 40979592, 2025). "The results revealed that a high level of ASPM expression was significantly and positively correlated with the proliferation and invasion ability of tumor cells." (PMID 40979592, 2025). "We used Cox regression analysis to explore the tumor types affected by the ASPM gene, and the results revealed that overall survival (OS) was correlated with ASPM in 14 tumor types." (PMID 40979592, 2025). "By silencing the ASPM gene, the proliferation and invasive activity of tumor cells can be effectively inhibited." (PMID 40979592, 2025). "More interestingly, we also found that TLS score was negatively correlated with tumor proliferation biomarkers, such as ASPM and KI67, which explained the correlation of the presence of TLS with better prognosis." (PMID 38709170, 2024). "ASPM, which is involved in mitotic spindle regulation and coordination of mitotic processes, has already been identified as a tumor marker in other settings." (PMID 38903178, 2024). "Further functional studies of ASPM with consideration of its subcellular localization in tumor cells are warranted." (PMID 39594769, 2024). "Nude mice receiving ASPM knockdown T24 cells developed smaller tumors with lower tumor proliferative activity, indicating a significant role of ASPM in BLCA proliferation and tumorigenesis." (PMID 37051591, 2023). "The tumor mutation burden (TMB) of these genes was also analyzed, and ASPM, CENPF, and POLQ had higher mutation rates than the other genes." (PMID 37077308, 2023).
tumor (continued). "Yuan at al. confirmed that ASPM, FOXM1, RACGAP1, and TPX2 were significantly associated with not only tumor progression but also prognosis of ACC." (PMID 35693556, 2022). "The expression of ASPM was higher in all LIHC tumor tissues than in normal tissues, with that in grade 3 tissues being statistically significant." (PMID 35515103, 2022). "Compared with adjacent non-tumor tissues, the expression level of ASPM in HBV (+) HCC tissues (n = 145) was significantly higher than that in HBV (-) HCC tissues (n = 226)." (PMID 36304312, 2022). "Given the oncogenic role of ASPM in vitro, we next sought to explore its tumorigenicity in a xenograft tumor model." (PMID 35387319, 2022). "The IHC analysis of tumor tissues showed a significant decrease of ASPM expression in the ASPM-knockdown group." (PMID 35387319, 2022). "The relationship between ASPM expression and tumor immunity was analyzed using the TIMER and GEPIA databases, and the results were further verified using qPCR, western blot, and multiplex quantitative immuno fluorescence." (PMID 35515103, 2022). "Abnormal spindle protein homolog (ASPM) was detected in circulating tumor cells through single-cell genomic characterization in cancer patients." (PMID 35884419, 2022). "We investigated ASPM expression on the basis of histological subtype, tumor grade, and other patient conditions using the UALCAN database." (PMID 35515103, 2022). "In the early stage of HCC, the ASPM expression levels were also increased, and the closer to the tumor center, the higher the level of its expression." (PMID 36304312, 2022). "This suggests a role for ASPM in regulating the tumor-infiltration of B cells, CD8+ T cells and M2 macrophages." (PMID 35515103, 2022). "Concerning PAAD tumors, on the basis of tumor grade, ASPM expression was higher in all tumor tissues than in normal tissues, and the increase was statistically significant for PAAD in grade 3." (PMID 35515103, 2022). "ASPM expression and its influence on tumor prognosis were analyzed using the Tumor Immune Estimation Resource (TIMER), UALCAN, OncoLnc, and Gene Expression Profiling Interactive Analysis (GEPIA) databases." (PMID 35515103, 2022). "Regarding patients’ smoking habits, all histological subtypes of LUAD tumor showed increased ASPM expression compared with normal tissues, we found that ASPM expression was higher in patients who smoked longer (p < 10-6)." (PMID 35515103, 2022). "ASPM expression showed a strong correlation with tumor-infiltrating B cells, CD8+ T cells, and M2 macrophages in KIRC and LIHC." (PMID 35515103, 2022). "For the pathways distribution from the KEGG database (c2.cp.kegg.v7.0), ASPM, CENPF, and PRC1 shared three important tumor-associated terms (KEGG_CELL_CYCLE, KEGG_OOCYTE_MEIOSIS, and KEGG_SPLICEOSOME) in the top five significant pathways." (PMID 33946043, 2021). "The median levels of ASPM mRNA expression in tumor tissues of all five groups were higher than those in the adjacent nontumor tissues, although they were not statistically significant in HCC and MLC groups because of limited samples." (PMID 34428354, 2021). "In a primary mouse model of MB, conditional ASPM deletion impairs tumor growth, increases DNA damage, and reduces hydrocephalus." (PMID 34663805, 2021). "The protein expression of ASPM was higher in 73.8% (48/65) and 71.9% (23/32) of tumor tissues, respectively." (PMID 34428354, 2021). "This evidence indicated that inhibition of ASPM can repress the formation and growth of subcutaneous tumours." (PMID 32667745, 2020). "First of all, we obtained hub genes by taking the intersection between DEGs of TCGA and GEO,finding that BCHE, MAL and ASPM are tumor-related genes and can be used as potential biomarkers in EC treatment." (PMID 32099532, 2020). "Immunohistochemistry staining showed the higher expression of ASPM in the tumor sample compared with the normal sample." (PMID 32099532, 2020).
tumor (continued). "Whereas the expression level of ASPM in tumor tissues was obviously related to tumor size (P=0.024) and clinical stage (P=0.021)." (PMID 32742488, 2020). "Using UALCAN, we found that MAL and ASPM expressed higher in tumor than in normal tissues, both negatively related to the overall survival of the EC patients." (PMID 32099532, 2020). "In our study, we used the immunohistochemistry to observe the association between the expression of ASPM and CDK4 in tumor tissue by uninterrupted slicing." (PMID 32742488, 2020). "Recently, ASPM is reported widely expressed in multiple tumor tissues and involved in the development and progression of several cancers." (PMID 32742488, 2020). "In fact, ASPM depletion blocks neural stem cell and tumor cell proliferation, thereby affects neurogenesis and tumor growth." (PMID 32742488, 2020). "In the context of PDAC, ASPM promotes Wnt activity to regulate cancer stemness and thus enhances tumor progression." (PMID 30092011, 2018). "Analysis of the validation set using continuous data analysis revealed low levels of cytoplasmic ASPM significantly correlated with high-grade tumours in the serous subtype (p<0.001)." (PMID 24830737, 2014). "In primary cultures of malignant cells derived from ovarian ascites samples we had determined that cytoplasmic ASPM levels decreased with tumour grade." (PMID 24830737, 2014). "Cytoplasmic ASPM levels were also found to be associated with tumour invasiveness with highest cytoplasmic ASPM levels found only when the tumour remained confined to the ovaries (T1)." (PMID 24830737, 2014). "Microcephalin and ASPM expression levels were further assessed in the context of disease severity as determined by the level of tumour invasiveness (T1, T2 and T3)." (PMID 24830737, 2014). "We have validated previous findings of deregulated expression of Microcephalin and ASPM in EOC by confirming associations for low nuclear Microcephalin levels and high cytoplasmic ASPM levels in a larger scale tumour tissue study." (PMID 24830737, 2014). "Although cytoplasmic and nuclear locations of ASPM in other tumour types have been noted in the literature so far there is little information about the role of this differential location of ASPM, especially with regards to EOC." (PMID 24830737, 2014). "Cytoplasmic ASPM expression decreased with tumour grade and stage in the serous subtype of EOC (p = 0.023 and p = 0.011 respectively)." (PMID 24830737, 2014). "Similar trends for the cell-cycle-associated genes (ASPM, CENPE, TPX2, TRIP13, KIF11, KIF20A) were observed with their distribution in different-grade tumors, with higher expression levels observed as tumor grade increased." (PMID 23506684, 2013). "Due to loss of biopsy cores, insufficient tumor cells present in the cores or affluence of necrotic tissue, 72/80 FFPE specimens were evaluated for CCNB2, KIAA0101, SLC27A2, ASPM, and CDCA7 immunostaining." (PMID 23282137, 2013). "The majority of the 18 tumour-derived samples had both weak nuclear and weak cytoplasmic staining (64.7 and 77.8%, respectively), whereas 50% of the samples had weak mitotic ASPM staining." (PMID 21505456, 2011). "A statistically significant correlation was identified for ASPM localisation and tumour grade, with high levels of cytoplasmic ASPM correlating with grade 1 tumours." (PMID 21505456, 2011). "Analysis of the data revealed that with increasing tumour grade there was an increase in total ASPM protein in the sample set." (PMID 21505456, 2011). "In this study, we report that ASPM expression is correlated with tumor grade and increases at recurrence or after consecutive passages in vitro and in vivo." (PMID 20142996, 2010). "ASPM mRNA expression was measured in 11 recurrent tumors and compared to the initial tumor (3 Grade II, 1 Grade III and 7 Grade IV)." (PMID 20142996, 2010). "In the future, targeting ASPM may have biological consequences distinct from targeting microtubules upon the appearance of RT‐resistant tumor cells." (PMID 40873651, 2025).
tumor (continued). "Furthermore, a meta-analysis identified KIF20A and ASPM among the top 55 overexpressed genes when comparing tumor and normal samples across the ten most frequent human cancers." (PMID 37835564, 2023). "In addition, the same genes can generate multiple relevant TAAs across tumor samples, with three unique TAAs being derived not only from the ASPM gene but from the same transcript (among these, SANVSKVSF was validated)." (PMID 35367648, 2022). "Indeed, inhibiting ASPM expression results in an increase in DNA damage and sensitization of both immortalized cells and tumor cells to ionizing irradiation (IR)." (PMID 34142045, 2021). "To investigate the relationship between ASPM and tumour immunity, we analysed the relationship between ASPM and immune cell infiltration via the TIMER website, and we found that ASPM is involved in the infiltration of CD8+ T cells, neutrophils, and dendritic cells in BLCA." (PMID 32047816, 2020). "ASPM ablation obviously blocked proliferation in vitro and suppressed tumor growth in mice." (PMID 32742488, 2020). "To investigate whether the ASPM gene acts as an oncogene in other tumours, we analysed the differential expression of ASPM in different tumours and normal tissues via the TIMER website." (PMID 32047816, 2020). "And the corresponding non-tumor normal tissues showed significant low expression of ASPM." (PMID 32742488, 2020). "Herein, we found that ASPM ablation reduced the expression levels of CCND1 and CDK4, which may cause the disorder of LSCC cell cycle and further block cell proliferation and tumor development." (PMID 32742488, 2020). "BCHE, MAL and ASPM are tumor-related genes and can be used as potential biomarkers in EC treatment." (PMID 32099532, 2020). "Knockdown of ASPM inhibited tumor growth and resulted in cell death." (PMID 31106147, 2019). "Similarly ASPM cytoplasmic staining decreased with increasing tumour stage when using the FIGO staging system (p = 0.0032)." (PMID 24830737, 2014). "Similarly to Microcephalin expression, in this study we recapitulated our recent findings on cytoplasmic ASPM levels and tumour grade." (PMID 24830737, 2014). "In contrast, ASPM mRNA levels were increased in tumour and transformed human cells." (PMID 24830737, 2014). "Furthermore, the ASPM protein is over-expressed in various cancers and its knockdown inhibits tumor proliferation." (PMID 23282137, 2013). "In addition to its role in embryonic development, ASPM is highly expressed in many tumor cell lines, suggesting an important involvement of this gene during tumorigenesis." (PMID 20142996, 2010). "ASPM mRNA, measured by RT-PCR, increased progressively with successive tumor passages." (PMID 20142996, 2010). "However, the relationship between ASPM expression, tumor immunity, and the prognosis of different cancers remains unclear." (PMID 35515103, 2022). "Therefore, we hypothesized that ASPM expression was associated with immune infiltration in KIRC, KIRP, LIHC, LUAD, and PAAD, and could be a potential marker of the tumor immune microenvironment." (PMID 35515103, 2022). "However, whether FoxM1 plays a role in tumour development by transcriptional regulation of ASPM expression is still unknown." (PMID 32667745, 2020). "Moreover, we found that ASPM, NEK and CCT3 over-expression present significant association with overall survival of HCC patients based on TCGA validation, predicting enhanced invasive/metastatic potential of HCC and higher risk of early tumor recurrence." (PMID 28086821, 2017).
tumor (continued). "Here, we demonstrate for the first time that ASPM and microcephalin protein expression is deregulated in primary cultures of malignant cells obtained from ascitic fluids of EOC patients and that this expression shows an association with survival or tumour grade." (PMID 21505456, 2011). "This study identified ASPM as a novel regulator of EGFR-TKI resistance in NSCLC, with dual roles in promoting tumor aggressiveness and stabilizing EGFR signaling." (PMID 40979592, 2025). "Six of them (KIF4A, ASPM, KIF20A, KIF14, TPX2, KIF18B) warrant particular attention as they show increased expression by more than 10-fold in tumor samples compared to normal tissues." (PMID 37835564, 2023). "Six of them (KIF4A, ASPM, KIF20A, KIF14, TPX2, KIF18B) are overexpressed by more than 10-fold in tumor samples and four of them (KIF11, AURKB, TPX2 and KIFC1) are essential for cell survival." (PMID 37835564, 2023). "Taken together, the results suggest that ASPM significantly promotes the proliferation, migration and invasion of HCC cells in vitro and tumor formation in nude mice." (PMID 34428354, 2021). "Down‐regulation of ASPM expression inhibits the proliferation, invasion, migration and epithelial‐to‐mesenchymal transition of HCC cells in vitro and inhibits tumor formation in nude mice." (PMID 34428354, 2021). "In vivo, ASPM’s high expression was shown to enhance the tumorigenicity of GBM xenograft model and its depletion resulted in reduced tumor growth." (PMID 34663805, 2021). "To investigate the relationship between CDC20, ASPM, and tumour immunity, we analysed the relationship between CDC20, ASPM, and immune cell infiltration via the TIMER website." (PMID 32047816, 2020). "In the datasets GSE25055 and GSE42568, higher expression levels of ASPM, CDC20, and TTK correlated with advanced tumor grades." (PMID 31106147, 2019). "As cell-cycle dependent proteins with interrelated functions, TOP2A, TPX2, and ASPM play key roles in the mitotic machinery that drives tumor cell replication in NSCLC and other tumor types." (PMID 31816603, 2019). "Both in the dataset GSE25055 and GSE42568, higher expression levels of ASPM, CDC20, and TTK were related to advanced tumor grades." (PMID 31106147, 2019). "In this study we investigated the expression of two MCPH proteins, Microcephalin and ASPM, in EOC tumour tissue samples." (PMID 24830737, 2014). "In the 7 patients whose initial tumor was a GBM, ASPM expression was 3.5-fold higher in the recurrent tumor although the grade did not change (p < 0.005)." (PMID 20142996, 2010). "qPCR analysis were performed for the genes KIF11, ASPM and MT3 in the tumours previously analyzed by gene-expression microarray." (PMID 20885975, 2010). "When specificially examining the tumor samples alone, we found that the cycling HepT population expressed high levels of EZH2, SUZ12, and EED, along with cell cycle regulators MKI67, AURKB, ASPM, TOP2A, and HELLS." (PMID 40766612, 2025). "The knockdown of ASPM inhibited TNBC growth and killed tumor cells in vitro." (PMID 39409999, 2024). "ASPM may play an important role in the microenvironment of KIRC and LIHC by regulating tumor infiltration of immune cells." (PMID 35515103, 2022). "Hence, our study suggests that ASPM is a potential biomarker for KIRC and LIHC prognosis and the status of tumor immunity." (PMID 35515103, 2022). "In the paired tumor and adjacent nontumor tissues, ASPM mRNA overexpression was found in 69 of 90 (76.7%) samples." (PMID 34428354, 2021). "Interestingly, many of these genes are known to be involved in cell-cycle function (CDK2, CDK6, CCNB1, CEP55, CENPF), transcriptional regulation/tumor suppression (FOXO3, TOP2A), DNA-damage response (ASPM, XRCC4), and tumor progression (CYR61, MACC1, CXCR4)." (PMID 28482906, 2017). "However, SAHA significantly enhanced the tumor initiating capacity and the expression of malignant genes such as KCNMA1, MORF4L2 and ASPM in the remaining living ALDHbr cells." (PMID 25796627, 2015).